CD33 (CD33 molecule)
Diseases named in the same sentence as CD33 in open-access papers (continued):
Sharing a sentence is not in itself a finding about the gene and the disease.
leukemia (continued). "A treatment study was designed to evaluate the therapeutic efficacy of [225Ac]Macropa-PEG4-7065, with groups including vehicle control, non-targeting [225Ac]Macropa-PEG4-IgG, the previously evaluated leukemia RIT [225Ac]DOTA-anti-CD33, and [225Ac]Macropa-PEG4-7065." (PMID 41282197, 2025). "The absence of bystander toxicities was confirmed by inoculating engrafted mice with the CD33+ MOLM-14 AML cell line: CD33.CAR-T cells were able to achieve tumor control in mice engrafted with either CD33-KO – or control HSCs, but caused off-leukemia toxicities only in the latter scenario." (PMID 38887285, 2024). "CD33-TriTE induced powerful cytotoxicity on leukemia cells with high PD-L1 expression." (PMID 35680594, 2022). "As a modular part of our nanocarrier system, siRNA can be designed and synthetized against any oncogenic factor and we here propose a targeted siRNA-transport system composed of an anti-CD33-antibody, protamine and siRNA that efficiently targets the leukemia-related oncogenes DNMT3A and FLT3." (PMID 36457063, 2022). "Previous studies reported that CAR-T cells targeted CD33/CD123, which antigens targeted both leukemia cells and hematological stem cells, indicating CD33/CD123 CAR-T treatment might result in the bone marrow failure." (PMID 35990606, 2022). "Most importantly, CD33 CAR-T cells showed efficient elimination of leukemia, while CD33-deficient cells were spared without myelotoxicity, as observed in human xenograft models." (PMID 36523990, 2022). "Furthermore, CD28-based CD33 CAR-T cells exhibited superior anti-leukemia compared with 4-1BB, and the safety and efficacy in patients were evaluated in a phase I clinical trial." (PMID 36523990, 2022). "Furthermore, we demonstrated an enhanced leukaemia suppression of an AML cell line xenograft model using FLT3‐ITD ASO loaded CD33‐targeting RBCEVs and in patient‐derived xenograft models of AML using miR‐125b ASO loaded CD33‐targeting RBCEVs." (PMID 35851970, 2022). "In analogy to the targeting of Siglec‐3/CD33 human leukemias, a similar approach could be taken for treatment of late‐stage carcinomas." (PMID 33615152, 2021). "CD33, a surface biomarker, is expressed on leukemia blasts from the majority of AML patients." (PMID 34775232, 2021). "Blocking the PD-1/PD-L1 pathway can increase the cytotoxicity of CD33/CD3 BiTE to leukemia cells." (PMID 31616632, 2019). "Therefore, the cytolytic activity of the CD33 CARs was directly related to the levels of CD33M expression by the leukemia target lines." (PMID 30524966, 2018). "These CD33-deficient cells then allow CD33-targeted CAR-T therapy for efficient elimination of CD33+ leukemia without myelotoxicity." (PMID 30577797, 2018). "CD45+CD33+ cells (leukemia blasts) in peripheral blood could be detected at the end stage of leukemia development and extensive infiltrations of AML cells could be detected in bone marrow, liver, and spleen confirmed by pathology and flow cytometry." (PMID 29716633, 2018). "Dual-specific targeting and elimination were investigated against the B-cell precursor leukemia cell line BV-173 and patient blasts, which were positive for myeloid marker CD33 and B lymphoid marker CD19 exclusively presented on biphenotypic B/myeloid leukemia’s." (PMID 28943878, 2017). "Furthermore, CD33 expression by leukemia cells from patients also seemed to be compatible with Notch-1 expression." (PMID 27233074, 2016). "The present study demonstrated that fucose-bound liposomes carrying daunorubicin could effectively target Notch-1/CD33 positive leukemia cells using the intrinsic requirement for L-fucose by such cells." (PMID 27233074, 2016). "We first analyzed the expression of CD33 and Notch-1 in various leukemia cell lines." (PMID 27233074, 2016). "Moreover, it enhanced the selective lysis of CD19/CD33 double-positive leukemia cells relative to CD19 single-positive targets with comparable target antigen density, which were present in the same reaction environment." (PMID 26981773, 2016).
leukemia (continued). "iC9-CAR.CD33 ATCs demonstrated potent effector functions towards CD33+ leukemia cell lines." (PMID 27907031, 2016). "The authors postulated that leukemia cells might have adopted other immune-evasion strategies enabling them to escape the killing by CAR.CD33 ATCs." (PMID 27907031, 2016). "Only CD33+ leukemic stem cells give rise to leukemia in mice." (PMID 26383821, 2015). "The study presented here shows that anti-CD33-antibody–protamine nanocarriers complexing anionic anti-cancer cargo such as siRNA or small molecules could represent a future-oriented possibility for leukemia therapy." (PMID 36457063, 2022). "We conclude that after i.p. injection, nanocarriers containing the carrier IgG as well as the siRNA are transported in vivo through the blood stream to xenografted cells of human origin expressing the CD33 antigen, may this be a subcutaneous tumor or an i.v.-engrafted primary leukemia." (PMID 36457063, 2022). "However, we detected a marked decrease in the stability of activated CD33+ NK cells during cytotoxic interactions against leukemia blasts confirmed by increased E/E cell contacts and higher effector cell clustering analyzed using fluorescence scanning microscope." (PMID 28943878, 2017). "Thus, the expression of CD33 and Notch-1 correlated in the same leukemia cell lines." (PMID 27233074, 2016). "The expression of human CD13 and CD33-positive tumor cells, which are considered to be the tumor marker of K562 cells, was high in BM and spleen in dying mice, which suggested that the mouse model bearing leukemia could be established." (PMID 26023795, 2015). "It uses two activating CARs (CD33 and FLT3) as an OR-gate to destroy leukemia cells with either antigen, countering tumor diversity." (PMID 41487532, 2025). "Loop33 and 123 CAR‐T cells targeting CD33 and CD123 eliminated AML cells and prolonged survival in leukaemia‐bearing mice, while mitigating immune escape." (PMID 41292193, 2025). "The primary targets for lymphoma and leukemia include CD19, CD123, CD22, CD33, and NKG2D ligands, while BCMA is the target for multiple myeloma." (PMID 40852706, 2025). "Overall, this experiment demonstrated the versatility of Val-ILs in targeting and inducing cell death in specific leukemia subtypes by incorporating different antibodies, such as anti-CD7 for T-ALL and anti-CD33 for AML." (PMID 38734740, 2024). "After the third cycle of myeloid-directed therapy, an interesting immunophenotypic shift was observed in which her leukemia cells exhibited increased CD19 and CD7 surface expression but decreased CD13 and CD33 expression." (PMID 38643442, 2024). "As a result, therapies, such as CD22/SIGLEC2 CAR-T and CD33/SIGLEC3 CAR-T, have been introduced to address refractory leukemia or lymphoma." (PMID 39697338, 2024). "GO-CD33 CAR-T cells showed significant toxicity in animal models, while lintuzumab-CD33 CAR-T cells were well tolerated and showed great anti-leukemia activity." (PMID 37296906, 2023). "The non-leukemic nature of the three monocyte/macrophage clusters was confirmed by low expression of leukemia myeloid markers (ITGAM, ANPEP, CD33)." (PMID 37798266, 2023). "From this perspective, prolonged inhibition of DOT1L seems to favor KMT2A-rearranged leukemia cells that completely lack PROM1/CD133 but do display LILRB4/CD85k and CD33 expression." (PMID 37740239, 2023). "Six stages of leukemia differentiation-arrest categories based on CD34, CD117, CD13, CD33, MPO, and HLA-DR expression were identified in two independent cohorts of 2087 and 1209 AML patients." (PMID 35973983, 2022). "These six CARs exhibited cytotoxicity against CD33+ AML cell lines in vitro and in vivo and showed strong anti-leukemia activity against patient-derived xenograft (PDX) derived from pediatric AML patients." (PMID 36523990, 2022). "After sufficiently expanding the PDX colony with ~1% human leukaemia cells in the peripheral blood, the mice were treated with miR‐125b ASO‐loaded CD33‐targeting/non‐targeting RBCEVs." (PMID 35851970, 2022).
leukemia (continued). "To determine the cellular uptake of CD33 targeting RBCEVs, we labelled CD33‐targeting and non‐targeting RBCEVs with CFSE dye before incubating them with leukaemia cells." (PMID 35851970, 2022). "The clinical trial results using CD33-CAR NK-92 cell infusion indicated that this therapy is safe, but exhibits low anti-leukemia efficacy." (PMID 36612114, 2022). "After the treatment period, one cohort of mice was sacrificed to measure the human leukemia burden in the bone marrow and spleen using antibodies against human AML immunophenotypic cell surface markers (hCD45+, CD13+, CD33+)." (PMID 33807974, 2021). "Different receptors like CD123, CD33, or CLL1 were found to be expressed in leukemia stem cells, but they are also expressed on normal stem cells and their expression varies across different subtypes of leukemia." (PMID 32993115, 2020). "Myeloid differentiation antigen CD33 is detected on blasts of > 85% of AML patients and also on leukemia stem cells (LSCs)." (PMID 33287858, 2020). "The expression of characteristic myeloid lineage markers CD13, CD33 and CD117 allows the distinction of AML from other types of leukaemias." (PMID 31086535, 2019). "On EHA meeting 2018, a team from China reported first-in-human results of a dual target combining CLL1 and CD33, where either antigen of CD33 and CLL-1 can elicit anti-leukemia activity of the compound CART (cCART)." (PMID 31014360, 2019). "Anti-CD33 CAR T cells exhibited anti-leukemia effects in NSG mice and killed primary CD33-expressing AML cells." (PMID 29466292, 2018). "We next established the anti-tumor properties of the 123b-33bcCAR against four primary patient leukemia samples, including two CD123+CD33+ AML and two CD123+ B-ALL samples (PT1:AML, PT2:B-ALL, PT3:AML, and PT4:B-ALL)." (PMID 29515236, 2018). "The cCAR targeted and responded to a variety of primary leukemia samples and efficiently ablated CD123+ LSCs and CD33+ AML bulk cells in these samples." (PMID 29515236, 2018). "These CD34+/CD38− leukemia stem-like cells displayed positivity of the myeloid markers CD13 (99.1%), CD33 (98.6%), and CD123 (93.7%), suggesting that certain myeloid features remain in these sorted CD34+/CD38− KG1α cells." (PMID 28518151, 2017). "So far all TMs described in our previous studies were directed against protein targets including CD33, CD123 in leukemias and PSCA, PSMA and EGFR in solid tumors." (PMID 29312553, 2017). "Trispecific (CD123, CD33, CD16) antibodies capable of redirecting NK cells (through CD16) to kill leukemia have also been developed." (PMID 27761200, 2016). "By targeting both tumor-associated antigens, i.e. CD19 and CD33, at the same time, selectivity of elimination may be achieved and immune escape will likely be reduced, because antigen double-negative leukemia cell clones are less likely to be selected than single-negative ones." (PMID 26981773, 2016). "More selective antigens for the AML leukaemia stem cell are under investigation (such as CD123 or CD44), in case of limiting myeloid toxicity related to the CD33 targeting." (PMID 22272203, 2012). "For leukemias with aberrant myeloid cells concordance was lower, in particular for the myeloid antigens CD13 and CD33." (PMID 23152841, 2012). "For the leukemia dataset, among the 10 top-ranked genes, two genes (ZYX and CCND3) are cancer ones, five (APLP2, CD33, SP3, CD63, PSME1) and one other genes (CST3) are directly or indirectly associated with cancer genes, respectively." (PMID 22830977, 2012). "In preclinical mouse models, CAR-NKT cells exhibit strong BM homing and effectively target BM-resident malignant blast cells, including CD33-low/negative leukemia stem and progenitor cells." (PMID 39893165, 2025). "Primary CD33-targeting CAR-NK cells strongly reduce the burden of leukemia and prevents BM transplantation of leukemia cells without significant side effects." (PMID 40726987, 2025).
leukemia (continued). "The cellular target for lintuzumab is the myeloid-specific transmembrane receptor CD33, which has high availability on leukemia cells while lacking expression in hematologic stem cells." (PMID 38256909, 2024). "We also load CD33‐targeting RBCEVs with antisense oligonucleotides (ASOs) targeting FLT3‐ITD or miR‐125b, 2 common oncogenes in AML, and demonstrate that the engineered EVs improve leukaemia suppression in in vitro and in vivo models of AML." (PMID 35851970, 2022). "Moreover, it is now possible to detect antibodies present in leukemia cells, such as CD52, CD38, CD33, CD20, CD25, CD19, and CD22, and target them with new antibody–drug conjugates." (PMID 35011701, 2022). "In addition to CD19, the clinical studies of CAR-NK cells in lymphomas and leukemia have also targeted CD7 (NCT02742727) and CD33 (NCT02944162)." (PMID 36077853, 2022). "CD33 is a member of the sialic acid‐binding immunoglobulin‐like lectin family, which is highly expressed on the majority of AML cells and is considered as a common leukaemia biomarker." (PMID 35851970, 2022). "Despite this biologic activity, we did not see anti-leukemia responses, although patients received only one dose of CD33-CAR-T cells, and this was the lowest dose level." (PMID 33833386, 2021). "Preclinical studies have shown that the AMG330′s anti-CD33 x anti-CD3 construct is cytotoxic even when target cells have low CD33 antigen density, making it a candidate to target a wide variety of CD33-positive leukemia including AML." (PMID 34203180, 2021). "In a mouse xenograft model the transplantation of CD33-ablated HSPCs with CD33-targeted immunotherapy leads to leukemia clearance, without myelosuppression." (PMID 34041025, 2021). "Healthy stem cells that lacked CD33 were able to function normally as well, making CD33 a unique marker for leukemia cells and enabling CAR-T cell therapy to easily identify and attack cancer cells." (PMID 34598686, 2021). "Subsequent administration of CART33 targeting CD33 was able to effectively eliminate CD33+ leukemia without notable off-target effects." (PMID 33415078, 2020). "The transmembrane glycoprotein CD33 is expressed on the surface of leukemia blasts in most patients with AML, but not on normal hematopoietic stem cells." (PMID 32117773, 2020). "In rhesus macaques, anti-CD33 CAR T cell therapy transfused after autologous CD33 knock-out HSPC transplantation was effective in eliminating leukemia cells without any signs of myelotoxicity." (PMID 30736352, 2019). "The most obvious characteristic in APL leukemia cells was the positive expression of MPO (+, 100%), CD13 (+, 100%; and homogeneous mean fluorescent intensity (MFI)), CD33 (+, 100%; and homogeneous MFI), CD64 (dim, 100%; and homogeneous MFI), and negative expression of CD11b (0%) and CD10 (0%)." (PMID 29113330, 2017). "Because CD33 is a notable and promising myeloid-specific target, many groups have independently designed CD33-directed CAR T cells and reported potent anti-leukemia outcomes using AML tumor cells and primary xenograft models." (PMID 28851445, 2017). "Notably, both mutational analyses and xenograft assays demonstrated that engrafted mice developed leukemia, irrespective of the CD33 expression on the transplanted human cells." (PMID 40362463, 2025). "In mouse models, CD33 knockout does not affect the differentiation ability, maintenance, or engraftment capacity of normal stem cells, and CD33-CAR T-cells cause a rapid clearance of leukemia cells in mice engrafted with CD33 KO HSCs." (PMID 39770471, 2024). "Similarly, another study observed a significant reduction in tumor burden within a leukemia mouse model treated with CD33-CAR-PB-NK cells, with no apparent side effects." (PMID 39007146, 2024).
leukemia (continued). "To evaluate the anti-leukemia effects of metabolism-enhanced T cells, we performed a proof-of-principle exploration by directly co-culturing engineered T cells and either allogenic MV4-11, an AML blast cell line, or primary AML patient derived-CD33+ blasts in vitro." (PMID 39457563, 2024). "Although efficacy was already achieved in clinical trials using CAR T cells directed against CD123 or combinations of CD33/CLL-1, these approaches will only benefit a minority of patients owing to their application as a bridge to transplant for avoiding profound on-target/off-leukemia activities." (PMID 37106163, 2023). "The identification of a very minor fraction of leukemia marrow cells that have a primitive Lin−, CD34+, CD19−, CD33−, CD38− phenotype and that contained the patient-specific leukemia karyotype suggests that B-cell precursor ALL may arise in a more primitive cell." (PMID 35216407, 2022). "CD16-directed BiKEs CD16 × CD19 and CD16 × CD33 and TriKE CD16 × CD22 × CD19 were shown to specifically stimulate NK cell activation via CD16, which triggers NK cell cytolytic activity and secretion of cytokines to attack CD19+, CD33+, and CD19+CD22+ lymphoma and leukemia, respectively." (PMID 33505304, 2020). "In vitro, CD16/CD33 BiKE ± ADAM 17 inhibitor enhances the activation and specificity of NK cells to CD 33 (+) AML, and may be used for recurrent AML or post-transplant anti-leukemia therapy in the future." (PMID 31616632, 2019). "Additionally, anti-CD33 redirected CAR T-cells could be used as a ‘bridge” therapy for patients coming to an allo-HSCT, as anti-leukemia activity from infusing CAR.CD33 T-cells has been demonstrated in an ongoing clinical trial." (PMID 27907031, 2016). "Furthermore, the fact that leukemia engraftment was observed in mice regardless of the CD33 expression in the injected human cells may question the specificity of this antigen as a leukemic marker." (PMID 40362463, 2025). "For example, CRISPR/Cas9-mediated deletion of CD33 in HSPCs preserved hematopoietic function while rendering cells resistant to CD33-directed CAR T cell cytotoxicity, enabling leukemia clearance without prolonged myelosuppression." (PMID 41463143, 2025). "Although the studied neutrophils are confirmed to be mature, CD33+CD15+ cells that are unlikely to be a progeny of leukemic clone, it cannot be excluded that their function might be affected by various disease-related factors independent from differentiation block that is a hallmark of leukemia." (PMID 33467555, 2021). "We therefore assessed the expression of CD33 and FLT3 (data not shown) in the same 15 leukemia and cord blood samples in order to demonstrate correlation between the RPKM and delta Ct (dCt) values for this gene." (PMID 24069164, 2013). "Interestingly, CD123 (the trans-membrane α chain of the IL-3 receptor), a molecule previously identified as a LSC-specific marker in AML and found to be co-expressed with CD33 in 70% of adult AML cases, was detected on LSCs, but not on bulk leukemia cells." (PMID 29466292, 2018).